EPHX2 (epoxide hydrolase 2)
Diseases named in the same sentence as EPHX2 in open-access papers (continued):
Sharing a sentence is not in itself a finding about the gene and the disease.
anorexia nervosa (2 papers, 2014 to 2024). A disorder most often seen in adolescent females characterized by a refusal to maintain a minimally normal body weight, an intense fear of gaining weight, a disturbance in body image, and, in postmenarcheal females, the development of amenorrhea. "A targeted sequencing project in anorexia nervosa (AN) patients claims an association between AN and the epoxide hydrolase 2 (EPHX2) gene, though the burden test p-value of the gene failed to meet exome-wide significance (discovery, p = 4 × 10−4; replication, p = 6.2 × 10−3)." (PMID 24705293, 2014).
Arrhythmia (2 papers, 2013 to 2022). Any cardiac rhythm other than the normal sinus rhythm. "Based on the role of EPHX2 in HF in knockout mice, it was found that EPHX2 gene ablation could prevent HF and arrhythmia caused by pressure overload." (PMID 36545315, 2022).
bladder cancer (2 papers, 2019 to 2025). "Our results indicated that EPHX2 expression was significantly lower in human bladder cancer cell lines (T24 and 5637) compared with the human ureter epithelial cell line (SV‐HUC‐1)." (PMID 40129060, 2025).
cerebrovascular disease (2 papers, 2014 to 2023). "A recent study also demonstrated significant association of EPHX2 genetic variation with cerebrovascular disease." (PMID 37143691, 2023). "In addition to rs473728, as a pre-screening marker for Aβ positivity in SVCI, our results support the possible therapeutic target of EPHX2 for cerebrovascular disease." (PMID 37143691, 2023).
congenital heart disease (2 papers, 2020 to 2021). A heart disease that is present at birth. "A study in humans reported that the EPHX2(K55R) variant, which results in elevated EPHX2 activity, increases the risk of congenital heart disease in Caucasians." (PMID 32192153, 2020).
emphysema (2 papers, 2017 to 2023). "In this way, Ephx2−/− mice are less susceptible to CS-induced emphysema and airway resistance and air space enlargement is greater in WT and Ephx2−/− mice in response to CS exposure but comparatively less in CS-exposed Ephx2−/− mice." (PMID 28028752, 2017). "Lm of CS-exposed Ephx2−/− mice was significantly lower compared with CS-exposed WT mice, indicating a partial protection against pulmonary emphysema." (PMID 28028752, 2017). "Adult male wild-type (WT) C57BL/6J and Ephx2−/− mice were exposed to air or CS for 12 weeks, and lung inflammatory responses, air space enlargement (emphysema), lung function, and autophagy were assessed." (PMID 28028752, 2017). "Lm was measured to quantify emphysema and CS-exposed WT and CS-exposed Ephx2−/− mice had greater alveolar size compared with corresponding air-exposed mice." (PMID 28028752, 2017). "In this way, the mechanism of repair of tissue in Ephx2−/− mice with emphysema may depend on EET properties." (PMID 28028752, 2017). "For this reason, we here investigated whether Ephx2 deficiency could modulate inflammation and autophagy in COPD and influences emphysema and lung function using Ephx2 (sEH) knockout (Ephx2−/−) and wild-type (WT) mice and a mouse model of CS-induced COPD." (PMID 28028752, 2017). "For this reason, the effect of decreased soluble epoxide hydrolase (sEH, Ephx2)-mediated EET hydrolysis on inflammation, emphysema, lung function, and autophagy was here studied in CS-induced COPD in vivo." (PMID 28028752, 2017).
gastric cancer (2 papers, 2021 to 2025). A primary or metastatic malignant neoplasm involving the stomach. "Further analysis showed that patients with low EPHX2 expression had a significantly shorter survival time than those with high EPHX2 expression, indicating that EPHX2 may be an important indicator for predicting the prognosis of gastric cancer." (PMID 40538850, 2025). "Meanwhile, the study also found that the expression level of the EPHX2 gene was significantly lower in metastatic gastric cancer tissues than in non-metastatic samples." (PMID 40538850, 2025).
IgA nephropathy (2 papers, 2012 to 2024). "We recently confirmed an effect of EPHX2 genetic polymorphisms on kidney transplantation and IgA nephropathy, the most common chronic glomerulonephritis." (PMID 22590647, 2012).
kidney transplant (2 papers, 2021). A surgical procedure in which one or both kidneys from a donor are implanted into a recipient. "The impact of single nucleotide polymorphisms (SNPs) in the sEH gene EPHX2 and CYP450 on renal and vascular function, plasma levels of EETs and peripheral blood monuclear cell sEH activity was assessed in 79 kidney transplant recipients explored at least one year after transplantation." (PMID 33580125, 2021). "Thus, the aim of this study was to carefully assess whether genetic variations in EPHX2 and CYP450 of kidney transplant recipients affect renal and vascular function taking into consideration their effects on EET metabolism." (PMID 33580125, 2021).
lupus nephritis (2 papers, 2019 to 2024). Glomerulonephritis in the context of systemic lupus erythematosus. "Gene expression of EPHX2 was significantly reduced in the kidneys of both NZB/W F1 mice and lupus nephritis (LN) patients." (PMID 31222024, 2019).
prostate tumor (2 papers, 2021 to 2024). "Because sEH is both a marker for and a cause of inflammation and tumorigenesis, we first measured gene expression of Ephx2, the gene that encodes sEH, in bladder and prostate tumors in mice treated with ICIs." (PMID 38330013, 2024).
sarcoidosis (2 papers, 2018 to 2022). Sarcoidosis is a multisystemic disorder of unknown cause characterized by the formation of immune granulomas in involved organs. "In addition, we found that LRRN3, IFI44, LHFPL2, RTP4, and EPHX2 were all involved in diagnosing sarcoidosis, which might shed light on the mechanisms of sarcoidosis and provide potential biomarkers for diagnosis." (PMID 36405616, 2022).
triple-negative breast carcinoma (2 papers, 2020 to 2024). An invasive breast carcinoma which is negative for expression of estrogen receptor (ER), progesterone receptor (PR), and human epidermal growth factor receptor 2 (HER2). "Stratification based on this cutoff value showed elevated EPHX2 expression in multiple clinicopathological features, including older age and nuclear grade, human epidermal growth factor receptor 2 (HER2) and triple negative breast cancer (TNBC) subtypes, and recurrence." (PMID 39125591, 2024).
acute coronary syndrome (1 paper, 2025). Signs and symptoms related to acute ischemia of the myocardium secondary to coronary artery disease. "Genetic studies have further identified EPHX2 variants associated with heightened cardiovascular risk, such as aortic aneurysm and dissection, while the Lys55Arg polymorphism in EPHX2 correlates with increased long-term mortality after acute coronary syndrome." (PMID 41472876, 2025).
acute myeloid leukemia (1 paper, 2025). Acute myeloid leukemia (AML) is a group of neoplasms arising from precursor cells committed to the myeloid cell-line differentiation. "Moreover, Cox OS analysis suggested that EPHX2 was a protective factor in ACC, CESC, KIRC, LUAD, MESO, PAAD, and UVM, but a risk factor in acute myeloid leukemia (LAML) and LGG." (PMID 40129060, 2025).
Anorexia (1 paper, 2017). Lack of desire to eat (loss of appetite). "However, it is important to mention that the SHR model presents polymorphisms in the gene that encodes the epoxide hydrolase (EPHX2), an enzyme related to renal metabolism of arachidonic acid, transient states of anorexia and imbalances in cholesterolemic levels after ingestion of fatty acids." (PMID 28763008, 2017).
bladder tumors (1 paper, 2024). "To determine whether Ephx2 gene induction was specific to ICI targeting PD-1, we utilized C57BL/6 mice inoculated with 1 × 106 MB49 bladder tumor cells which were randomized to receive treatment with systemic anti-CTLA-4 or vehicle." (PMID 38330013, 2024).
cancer of the oral cavity (1 paper, 2019). "Our present finding of downregulation of oxidative stress-related genes EPHX2 and GPX3, belonging to the AAM pathway, in OSCC-GB patients, is therefore notable; similar findings were also reported in cancer of the oral cavity." (PMID 31796082, 2019).
carotid atherosclerosis (1 paper, 2021). A thickening and loss of elasticity of the walls of carotid arteries that occur with formation of atherosclerotic plaques. "Having this background in mind, the aim of our study was to investigate the possible association between rs2741335 and rs11780592 EPHX2 polymorphisms with oxidized LDL (ox-LDL), carotid atherosclerosis, mortality, and CV disease in a cohort of T2DM patients with various degrees of renal function." (PMID 34040693, 2021).
cervical squamous cell carcinoma (1 paper, 2025). A squamous cell carcinoma arising from the cervical epithelium. "EPHX2 proved to be a valuable diagnostic biomarker in a range of tumor types, particularly in kidney renal clear cell carcinoma, cervical squamous cell carcinoma, and endocervical adenocarcinoma." (PMID 40129060, 2025). "For instance, decreased EPHX2 expression has been linked to poor prognosis in liver hepatocellular carcinoma (LIHC), and has been identified as a potential tumor suppressor in cervical squamous cell carcinoma." (PMID 40129060, 2025). "Correlation of the EPHX2 expression and the clinical characteristics of patients with kidney renal clear cell carcinoma (KIRC) and cervical squamous cell carcinoma and endocervical adenocarcinoma (CESC)." (PMID 40129060, 2025).
cholestasis (1 paper, 2023). Impairment of the bile flow caused by obstruction within the liver, or outside the liver in the bile duct system. "The genes regulated in all pathways, Cyp1a1, Cyp1a2, Cyp2a1, Cyp2b1, Cyp4a8, Cyp2c11, Rdh16, Alox15, Ephx2, Sult2a1, and Acox2, were the potential targets for ZYP treatment of cholestasis." (PMID 37881184, 2023).
diffuse large B-cell lymphoma (1 paper, 2025). "For DFS, EPHX2 was more likely to be a favorable factor in KIRC, PAAD, PRAD, and UVM, but deleterious in lymphoid neoplasm diffuse large B‐cell lymphoma (DLBC) and LGG." (PMID 40129060, 2025).
Huntington disease (1 paper, 2015). Huntington disease (HD) is a rare neurodegenerative disorder of the central nervous system characterized by unwanted choreatic movements, behavioral and psychiatric disturbances and dementia. "G-4 genes included 6 genes: Btg3 associated nuclear protein (Banp), Ephx2, retinoid X receptor gamma (Rxrg), Ryr1, RNA-binding protein fox-1 homolog 1 (Rbfox1) and Zbtb16 categorized as ‘hereditary disorder (Huntington's disease)'." (PMID 26165378, 2015). "In the present study, we investigated gene expression profiles in the kidneys, and unexpectedly found that 6 SHRSP-specific genes isolated from the rats at 6 weeks of age (Banp, Ephx2, Rbfox1, Rxrg, Ryr1 and Zbtb16) were annotated to ‘Huntington's disease'." (PMID 26165378, 2015).
hyperuricemia (1 paper, 2024). An abnormally high level of uric acid. "The results showed that DIO and its active metabolite DG regulate renal lipid metabolism through the EPHX2 gene, attenuate renal inflammatory reaction, and then promote the excretion of uric acid and reduce its reabsorption, which ultimately achieves the effect of treating plateau hyperuricemia." (PMID 39769164, 2024).
Infertility (1 paper, 2025). "To clarify the function of EPHX2 in EM‐GCs and EM‐associated infertility, we further overexpressed EZH2 after inducing oxidative stress." (PMID 40827571, 2025).
lipid metabolism disorder (1 paper, 2012). "We studied the role of sEH in lipid metabolism and the underlying mechanism in HF-diet–induced lipid metabolism disorder in mice with whole-body knockout of Ephx2 (sEH null) and their wild-type (WT) littermates." (PMID 22720061, 2012).
malignant brain tumor (1 paper, 2021). "The hydroxycarbonylation reaction was successfully used to construct DEL, and the known hits for soluble epoxide hydrolase (sEH, EPHX2), a cardiovascular target, and L3MBTL1, a member of the malignant brain tumor family, were further validated." (PMID 35424149, 2021).
mental disorder (1 paper, 2022). A disease that has its basis in the disruption of mental process. "Therefore, we speculate that EPHX2 may play its role in mental disorders through spatial working memory." (PMID 36176292, 2022).
mesothelioma (1 paper, 2025). A usually malignant and aggressive neoplasm of the mesothelium which is often associated with exposure to asbestos. "The results of KM OS analysis demonstrated that EPHX2 was identified as a protective factor for patients with ACC, CESC, KIRC, LIHC, Mesothelioma (MESO), PAAD, and uveal melanoma (UVM), and as a risk factor for patients with LGG." (PMID 40129060, 2025).
metastatic tumors (1 paper, 2025). "EPHX2, an enzyme involved in the metabolism of epoxyeicosatrienoic acids—bioactive lipid mediators derived from arachidonic acid—is typically downregulated in PCa but shows higher expression in metastatic tumors compared to localized cases." (PMID 40647540, 2025).
narcolepsy (1 paper, 2020). A sleep disorder characterized by a tendency for excessive sleepiness during the day which occurs even after adequate sleep in the nighttime. "Located within the gene, the functions PPP2R2C, GPM6A, EPHX2, NKAIN3, ZNF365, TENM4, and PR2Y11 are related to narcolepsy." (PMID 32358372, 2020).
neuroblastoma (1 paper, 2022). Neuroblastoma (NB) is the most common solid, extracranial childhood tumor. "Inhibitors of EPHX2 were reported to inhibit tau hyperphosphorylation and neuroinflammation in differentiated SH‐SY5Y human neuroblastoma cells." (PMID 35475262, 2022).
Opportunistic infection (1 paper, 2019). An infection that is caused by a pathogen that would generally not be able to cause an infection in a host with a normal immune system. "However, serious adverse events due to opportunistic infections and nephrotoxicity have occurred, further highlighting the potential advantages of EPHX2 inhibition as a differentiated therapeutic approach." (PMID 31002701, 2019).
osteosarcoma (1 paper, 2023). A usually aggressive malignant bone-forming mesenchymal neoplasm, predominantly affecting adolescents and young adults. "Combining literature reports and our results of bioinformatics and RT-qPCR, we hold that EPHX2 and FDPS are the oncogenes, while GBP1, MMD and ZYX are the anti-oncogene in osteosarcoma." (PMID 37090691, 2023).
renal carcinoma (1 paper, 2025). A carcinoma arising from the epithelium of the renal parenchyma or the renal pelvis. "Furthermore, EPHX2 expression was low in two renal cancer cell lines, A‐498 and 786‐O, relative to the human renal proximal convoluted tubular epithelial cell line (HK‐2)." (PMID 40129060, 2025).
renal cell carcinoma (1 paper, 2025). "It is imperative that future research addresses these limitations to enhance the dependability of EPHX2 as a biomarker and to elucidate its involvement in the molecular pathogenesis of renal cell carcinoma." (PMID 40538850, 2025).
renal clear cell carcinoma (1 paper, 2025). "The current study highlights the pivotal role of EPHX2 in the pathophysiology of renal clear cell carcinoma, indicating its promise as a therapeutic target and prognostic biomarker." (PMID 40538850, 2025). "The variations in EPHX2 expression across different TNM staging classifications, as well as the corresponding prognostic implications and clinical characteristics in clear cell renal cell carcinoma (ccRCC) tumors, are illustrated in." (PMID 40538850, 2025).
retinoblastoma (1 paper, 2025). A malignant tumor that originates in the nuclear layer of the retina. "The findings displayed that, in retinoblastoma (RB), EPHX2 expression had a positive relationship with angiogenesis, differentiation, inflammation, metastasis, quiescence, and stemness." (PMID 40129060, 2025).
skin cutaneous melanoma (1 paper, 2025). "Additionally, significant negative correlations were found between EPHX2 expression and DNA methylation in LGG, DLBC, UVM, LIHC, skin cutaneous melanoma (SKCM), ACC, and READ (r > 0.50, p < 0.05)." (PMID 40129060, 2025).
cardiovascular diseases (65 papers, 2008 to 2026). "Therefore, sEH, which is encoded in the EPHX2 gene located at chromosomal region 8p21-p12, has been known as the hydrolase to treat cardiovascular disease." (PMID 31991570, 2020). "In addition, CYP2C8, CYP2C9, and also EPHX2 genetic variants have been associated to myocardial infarction and cardiovascular disease." (PMID 25426071, 2014). "Accumulating evidence implicates EH family members, particularly Ephx1 (microsomal EH) and Ephx2 (soluble EH), in cardiovascular diseases, cancer, neurodegeneration, metabolic disorders, and other pathological conditions." (PMID 42117830, 2026). "Therefore, inhibition of EPHX2 to maintain high EET levels is considered to be a new target for clinical application in the treatment of cardiovascular diseases." (PMID 36545315, 2022). "Thus, sEH, which is encoded in the EPHX2 gene located at chromosomal region 8p21-p12, has gained attention as a therapeutic target for the treatment of cardiovascular disease." (PMID 32972033, 2020). "In addition, studies of polymorphisms in the gene encoding sEH (EPHX2) have shown that amino-acid substitutions can influence sEH activity in patients with cardiovascular diseases." (PMID 22590647, 2012).